INS (insulin)
Diseases named in the same sentence as INS in open-access papers (continued):
Sharing a sentence is not in itself a finding about the gene and the disease.
endothelial dysfunction (continued). "Here, we examined whether treatment with ET-1 antagonists BQ123/BQ788 or insulin (1 mU/mL and 10 mU/mL doses can reduce markers associated with endothelial dysfunction ET-1, VCAM1 and ICAM1." (PMID 37893034, 2023). "For instance, many fruits contain flavonoids, which scavenge free radicals, improve glucose tolerance and insulin sensitivity, modulate lipid metabolism and adipocyte differentiation, suppress inflammation and apoptosis, and improve endothelial dysfunction, thus reducing CVD risk." (PMID 36815021, 2023). "Moreover, reduced vasodilatation caused by the endothelial dysfunction hinders insulin and glucose in reaching the peripheral tissues and weakens glucose uptake stimulated by insulin." (PMID 35742943, 2022). "Furthermore, a high intake of saturated fats can interfere with insulin signaling, and it also induces inflammation and endothelial dysfunction, both pathogenic factors in GDM." (PMID 35889912, 2022). "In addition, the nitric oxide (NO) impairment observed in obese children was attributed to insulin dysfunction, which is a hallmark of endothelial dysfunction." (PMID 34299638, 2021). "Trans-fat may cause endothelial dysfunction, at least partially, by increasing NF-κB activation and impair insulin-mediated NO production in endothelial cells." (PMID 33062134, 2020). "NF-κB induces TNF-α signaling to accentuate oxidative stress and endothelial dysfunction induced via an IKKβ-dependent mechanism, which may be associated with inflammatory and insulin signaling pathways seen in T2DM." (PMID 30889182, 2019). "This pathway is impaired and associated to endothelial dysfunction in insulin resistant states." (PMID 30787881, 2019). "The mechanisms for this has yet to be defined, however one possible mechanism could be explained by the endothelial dysfunction caused by the blunting of insulin-induced endothelial nitric oxide synthase (eNOS) as a result of IR." (PMID 27422625, 2016). "Endothelial dysfunction characterized by impairment of endothelium-dependent vasodilatation can result from an increase in ROS and inflammation which will then lead to a loss of insulin-stimulated nitric oxide (NO) secretion." (PMID 27250532, 2016). "First, the endothelial dysfunction caused by increased uric acid levels may reduce the endothelial NO production, which plays a role in insulin action." (PMID 25617895, 2015). "Furthermore, insulin has been shown to be associated with endothelial dysfunction and it is known that patients treated with insulin often have reduced responsiveness to antiplatelet treatment." (PMID 23807613, 2014). "These considerations are also supported by our data as we found an inverse association between insulin sensitivity as well as subtle inflammation and indicators of endothelial dysfunction in our study of relatively young females at a very early stage of cardiometabolic disorders." (PMID 25281032, 2014). "Our present study shows that decreased GAG content in insulin alone treated cells may lead to endothelial dysfunction caused by GAG degradation and/or inhibition of GAG synthesis." (PMID 19695080, 2009). "In addition, many studies showed the development of fibrosis is associated with increased inflammatory state, endothelial dysfunction, insulin resistance and lipid metabolism, thereby forming a vicious circle which affects systemic vascular autoregulation and blood vessel walls." (PMID 35769370, 2022). "Hence, improving insulin sensitivity could potentially ameliorate endothelial dysfunction that underlies vascular neurodegeneration in glaucoma." (PMID 33925119, 2021). "Thus, insulin may also cause endothelial dysfunction through increased endothelin-1 availability and through downstream effects on NAD(P)H oxidase and superoxide anion production." (PMID 20334663, 2010). "Second, the core damage caused by IR to the vascular system lies in disrupting the dual-pathway balance of insulin signaling, leading to endothelial dysfunction." (PMID 41299267, 2025).
endothelial dysfunction (continued). "Oxidative stress can impair insulin signaling, promote vascular damage, and accelerate the progression of DR, while chronic inflammation contributes to endothelial dysfunction and retinal damage through the release of pro-inflammatory cytokines." (PMID 40234618, 2025). "Elevated Apo-B levels reflect an increased concentration of atherogenic particles, which can promote inflammation, endothelial dysfunction, and impaired insulin signaling, contributing to the pathogenesis of T2DM." (PMID 40423035, 2025). "The improving effects of probiotics on insulin sensitivity and inhibition of endothelium glycation are another way to prevent endothelial dysfunction." (PMID 40735396, 2025). "Endothelial dysfunction is one of the most frequently addressed issues related to endothelial function, with insulin playing a pivotal role in this context." (PMID 40283443, 2025). "IR contributes to endothelial dysfunction by impairing insulin signaling in endothelial cells and reducing the NO availability." (PMID 39621070, 2025). "Simultaneously, impaired insulin signaling pathways can result in endothelial dysfunction and a reduction in nitric oxide synthase activity, subsequently resulting in systemic vasoconstriction." (PMID 41202057, 2025). "Physical activity improves insulin sensitivity, lipid metabolism, and blood pressure, while smoking contributes to inflammation and endothelial dysfunction." (PMID 41301855, 2025). "Oxidative stress induces plaque aggregation, insulin signaling, DNA damage, and endothelial dysfunction, which further induce or exacerbate various diseases, including neurodegenerative diseases, metabolic diseases, and cancer." (PMID 40867803, 2025). "A 26-week HFHS diet induced endothelial dysfunction in the thoracic aorta of male Wistar rats, evidenced by diminished Phe-induced contraction and impaired insulin-mediated vasorelaxation." (PMID 41439140, 2025). "In summary, our findings suggest that cPLA2 plays a central role in oTau-induced abnormalities in insulin signaling and endothelial dysfunction in the brain." (PMID 41280311, 2025). "At the cellular level, perturbations in insulin signaling pathways further exacerbate endothelial dysfunction and promote foam cell formation." (PMID 40474525, 2025). "CGM enables real-time glucose monitoring, allowing for precise insulin dosing and minimizing fluctuations that contribute to systemic inflammation and endothelial dysfunction, which are key factors in ED." (PMID 39337164, 2024). "Experimental studies have shown that women with PCOS exhibit endothelial dysfunction (impaired endothelium-dependent vasodilation) and reduced responses to the vasodilation effect of insulin." (PMID 38541997, 2024). "IR, characterized by impaired insulin action and elevated glucose levels, leads to dysregulated lipid metabolism, inflammation, endothelial dysfunction, and oxidative stress." (PMID 38388437, 2024). "Over-activation of RAAS interferes with insulin action in blood vessels, muscles, and fats resulting in insulin resistance leading to gradual system breakdown by inducing endothelial dysfunction and the development of vascular complications." (PMID 39561140, 2024). "Several studies have suggested that inflammation and impaired insulin signaling pathways can lead to endothelial dysfunction." (PMID 38541997, 2024). "This can impact β cell insulin secretion, induce inflammatory responses, trigger endothelial dysfunction, myocardial damage, and contribute to cardiometabolic diseases." (PMID 38405061, 2024). "They proposed that insulin directly or indirectly promotes premature birth through inflammation, oxidative stress, and endothelial dysfunction." (PMID 39835257, 2024). "This lipid triad, along with endothelial dysfunction induced by aberrant insulin signaling, contributes to the formation of atherosclerotic plaques." (PMID 39726950, 2024).
endothelial dysfunction (continued). "Free-fatty-acid-mediated endothelial dysfunction involves several mechanisms, including impaired insulin signaling and nitric oxide production, oxidative stress, inflammation, and the activation of the renin–angiotensin system and apoptosis in the ECs." (PMID 39770410, 2024). "These lipid changes, along with endothelial dysfunction induced by abnormal insulin signaling, contribute to the formation of atherosclerotic plaques." (PMID 39713052, 2024). "FFA-mediated endothelial dysfunction involves multiple mechanisms, including impaired insulin signaling and nitric oxide production, oxidative stress, inflammation, activation of the renin-angiotensin system, and endothelial cell apoptosis." (PMID 39713052, 2024). "This leads to increased levels of free circulating androgens, which inhibit lipolysis and promote lipogenesis, resulting in insulin resistance, visceral fat accumulation, and endothelial dysfunction." (PMID 38375191, 2024). "The toxic effect of MGO has been extensively studied mostly in diabetic settings, especially its involvement in inducing diabetic sensorimotor polyneuropathy (DSPN), neuropathic pain, endothelial dysfunction, and functional alterations of human insulin." (PMID 39687678, 2024). "Free fatty acids modulate endothelial dysfunction through programmed cell death, inflammation, autophagy, mitochondrial dysfunction, ROS, ER stress, and insulin resistance in endothelial cells." (PMID 39765815, 2024). "Research is needed at the molecular-cellular level to tie together derangements in insulin action, cytokines, myokines, and endothelial dysfunction with clinical outcomes." (PMID 39459434, 2024). "Prior trials demonstrated that SGLT2i not only promotes glucose-lowering, but also improves endothelial dysfunction, adiposity, fluid overload, and insulin sensitivity thus contributing to hemodynamic changes implicated in its cardiorenal benefits." (PMID 37822556, 2023). "One of the miRs we studied is miR-15a-5p, secreted mainly in the pancreas, which is involved in the regulation of pancreatic cell maturation and differentiation, insulin secretion, glucose metabolism, as well as angiogenesis and endothelial dysfunction." (PMID 37629307, 2023). "ApoC-III activates protein kinase C beta (PKC β) which inhibits insulin signaling in ECs through eNOS pathway and the production of NO in ECs, thus determining endothelial dysfunction." (PMID 36689070, 2023). "The proinflammatory state leads to dysregulated insulin metabolic signalling within insulin sensitive tissues as well as pancreatic β cell dysfunction, insulinopenia and endothelial dysfunction." (PMID 37510962, 2023). "These include increased inflammation in adipose tissue, enhanced cholesterol synthesis in the liver, impaired insulin secretion, insulin resistance, compromised vascular tone and integrity, endothelial dysfunction, and atheroma formation." (PMID 38039549, 2023). "Genetics and epigenetics, altered lipid metabolism, systemic inflammation, systemic insulin resistance, plaque formation, oxidative stress, altered gut microcbiome, and endothelial dysfunction are proposed as the possible contributing mechanisms." (PMID 37749528, 2023). "Blood pressure (BP), body composition, heart rate variability (HRV), glycated hemoglobin (HbA1C), markers of insulin resistance, oxidative stress, inflammation and endothelial dysfunction, were assessed." (PMID 37365247, 2023). "Disorders of insulin sensitivity and lipid metabolism have also been reported to result in endothelial dysfunction." (PMID 37838692, 2023). "Resistance to insulin can trigger inflammatory processes, lipid metabolism deregulations, sympathetic nervous system over-activation, endothelial dysfunction, and eventually, thrombosis and CHD." (PMID 37542255, 2023).
endothelial dysfunction (continued). "Second, LFS and CAD share many pathophysiologic mechanisms, including systemic inflammation, endothelial dysfunction, hepatic insulin resistance, oxidative stress, and altered lipid metabolism." (PMID 35956339, 2022). "No other significant correlations were found for other co-morbidities, implying that the endothelial dysfunction of insulin-resistant states was crucial in hyperpermeability and disease severity." (PMID 36289641, 2022). "A MUFA-rich diet can improve insulin sensitivity, and positively affects blood lipids, systemic inflammatory response, and endothelial dysfunction." (PMID 36359131, 2022). "Treatment of OSA with continuous positive airway pressure (CPAP) has improved endothelial dysfunction, insulin sensitivity, decreased systemic blood pressure, pulmonary artery pressure, and reduced atrial fibrillation risk." (PMID 35336830, 2022). "Since the hemodynamic effects of insulin require phosphorylation of eNOS, endothelial dysfunction reduces blood flow to skeletal muscles, thus forming a vicious circle in which endothelial dysfunction worsens IR." (PMID 35330934, 2022). "OSM, MCP‐2, TGF‐α, and CXCL6 are likely to have an association with endothelial dysfunction and some are mostly or additionally involved in IR (MCP‐1, FGF‐21, TRAIL, and ADA) or insulin metabolism (TNFSF14/LIGHT)." (PMID 36467791, 2022). "There are multiple underlying mechanisms by which FLD increases the risk of CVD, such as systemic inflammation and oxidative stress, hepatic insulin resistance, platelet activation, endothelial dysfunction, and so on." (PMID 35647047, 2022). "Target mechanisms for new medications include increasing insulin sensitivity, reducing appetite, decreasing pro-inflammatory cytokines release by adipose tissue, and counteracting both endothelial dysfunction and thrombogenic effects of MS." (PMID 35800021, 2022). "Flavonoids, such as nobiletin, were reported to scavenge free radicals, improve glucose tolerance and insulin sensitivity, modulate lipid metabolism and adipocyte differentiation, suppress inflammation and apoptosis, and ameliorate endothelial dysfunction." (PMID 35872979, 2022). "Short-term feeding with HFD resulted in early endothelial dysfunction in coronary microcirculation that preceded alteration in cardiac function and systemic insulin resistance." (PMID 34556779, 2021). "Changes in insulin-dependent vasorelaxation cannot be fully explained by the emerging endothelial dysfunction as it robustly affects both VDD groups, differently from ACh relaxation." (PMID 33791074, 2021). "Estrogen withdrawal at menopause results in alterations in endothelial dysfunction, vascular inflammation, sympathetic tone, and a higher insulin resistance." (PMID 34569250, 2021). "In this way, insulin-resistant subjects carrying IRS-1 polymorphisms showed that impaired endothelial insulin signaling and reduced NO activity contributed to endothelial dysfunction." (PMID 34440804, 2021). "Results from the genome-wide association data suggest that shared biological processes contribute to the risk of migraine and coronary artery disease, and they point to the genes controlling for endothelial dysfunction and insulin homeostasis." (PMID 34098909, 2021). "Impairment in shared PI3K-dependent insulin signaling leads to reciprocal relationships between IR and endothelial dysfunction." (PMID 33708129, 2021). "In this sense, a very recent study of our group has shown how the administration of OLE to old rats for 3 weeks improves hepatic insulin sensitivity and attenuates endothelial dysfunction and insulin vascular resistance." (PMID 34067004, 2021). "Normally, insulin has vasodilatory effects, but in obese hyperinsulinemic persons, this response is reduced due to endothelial dysfunction, leading to increased vasoconstrictor tone." (PMID 34684310, 2021).
endothelial dysfunction (continued). "The RAAS can be upregulated by abnormal lipid levels or altered glucose/insulin levels as well, which leads to endothelial dysfunction and increased vascular superoxide production." (PMID 34733402, 2021). "The ER stress response is now recognized as a converging molecular mechanism connecting insulin resistance, lipid metabolism distress, and oxidative stress to endothelial dysfunction, and cell death." (PMID 33995826, 2021). "It is known that adropin participates in the regulation of energy homeostasis and insulin response, closely related to the development and progression of atherogenesis, having the positive effect on endothelial dysfunction." (PMID 34572509, 2021). "This work presents a critical review of inositol actions on insulin signaling, oxidative stress, and endothelial dysfunction, and its potential for either preventing or delaying cognitive impairment in aging and neurodegenerative diseases." (PMID 32825356, 2020). "In turn, induced endothelial dysfunction impairs insulin action due to damage of microcirculatory blood flow and the capillary network, reducing the motility of insulin in the circulation." (PMID 33042016, 2020). "NO metabolites, NO synthase inhibitors, and N-acetyl-β-glucosaminidase (NAGase) are biomarkers capable of measuring endothelial dysfunction and oxidative stress in the early stages of impaired response to insulin." (PMID 32630452, 2020). "A regular intake of dietary fibers in sufficient amounts can improve insulin sensitivity, metabolic homeostasis, and endothelial dysfunction, prevent against obesity, and regulate inflammatory biomarkers." (PMID 32668581, 2020). "This high degree of vulnerability is due tochanges in multiple physiological systems, primarily inflammation, insulin resistance,coagulation dysfunctions, endothelial dysfunctions, and vascular dysfunctions." (PMID 34178052, 2020). "Among the 12 animal RCTs reviewed, there were promising results for taurine supplementation on diabetic retinopathy, endothelial dysfunction, insulin sensitivity, and polydipsia/polyuria." (PMID 32341338, 2020). "Perturbation of endothelial functions in diseases such as diabetes and insulin resistance states disturb this balance leading to what is known as “endothelial dysfunction”." (PMID 33053883, 2020). "Elevated triglyceride levels as well as increased glucose and insulin concentrations are known to induce endothelial dysfunction by increasing inflammation, apoptosis, and mainly by increasing reactive oxygen species production." (PMID 32023876, 2020). "To improve/re-establish insulin sensitivity in patients with insulin-resistant endothelial dysfunction pharmacotherapy (thiazolidinediones, metformin, rosiglitazone) and lifestyle modifications are being implemented." (PMID 33117166, 2020). "Proposed pathways underlying this association include activation of the rennin-angiotensin-aldosterone system and increased procoagulatory activity, insulin resistance, sympathetic activity, leptin resistance, and endothelial dysfunction." (PMID 32172619, 2020). "In old rats, the treatment prevented aging-induced endothelial dysfunction, oxidative stress, inflammation, and vascular insulin resistance through activation of the PI3K/Akt pathway and decreasing the response to the vasoconstrictor angiotensin II." (PMID 32630452, 2020). "Mechanisms suggested to link glucose metabolism to PM2.5 with endothelial dysfunction, endoplasmic reticulum stress, insulin signaling abnormalities, and systematic inflammation." (PMID 32923347, 2020). "In diabetic rats, exercise training has been shown to normalize the diabetes-related endothelial dysfunction and improve insulin sensitivity." (PMID 33062134, 2020). "Insulin resistance is a major contributor to endothelial dysfunction since insulin plays key vascular functions." (PMID 33053883, 2020).